IL1B (interleukin 1 beta)
Diseases named in the same sentence as IL1B in open-access papers (continued):
Sharing a sentence is not in itself a finding about the gene and the disease.
tumor (continued). "At the molecular level, transcription factors such as STAT1, CEBPB, HIF1A, and REL, collectively drive MDSCs expansion, while chemokines like CCL3, CCL4, CCL8 and IL1B regulate their migration within the tumor microenvironment." (PMID 41252877, 2025). "A positive feedback loop between tumor cells and IL-1β-expressing TAMs further exacerbates the persistence of inflammation." (PMID 40861469, 2025). "IL-1β concentrations were higher in samples from patients with diagnosed coexisting non-neoplastic diseases." (PMID 40429943, 2025). "In one study, a 3D multicellular model for CRC was constructed using the CRC cell line SW480 with CAFs and endothelial cells, showing improved expression of several tumor-related genes including IL1B, FCGR2A, FCGR3A, CYBB, SPI1, CCL2, ITGAM, and ITGB2." (PMID 40376304, 2025). "IL-1B is a pro-inflammatory cytokine and plays a major role in the tumor environment to ensure cancer cell survival and growth." (PMID 39941709, 2025). "IL-1β suppresses anti-tumor immune responses by promoting Tregs, IL-6 promotes tumor growth and metastasis while inhibiting anti-tumor immunity, and IFN-γ activates CD8+ cytotoxic T lymphocytes, enhancing their tumor-killing ability." (PMID 39955603, 2025). "In this hypoxic state, macrophages are also oxygen-deprived, and HIF-1α stimulates tumor-associated macrophages (TAMs) to produce various factors, such as VEGF, IL-1β, TGF-β1, tumor necrosis factor (TNF)-α, basic fibroblast growth factor (bFGF), and IL-10." (PMID 40034694, 2025). "TNF-α promotes tumor cell death by killing T cells or other cells, and IL-1β and IL-6 play important roles in immune response and protein synthesis during the acute phase." (PMID 39857446, 2025). "Persistent expression of inflammatory factors produced within the tumor microenvironment, including GM-CSF, G-CSF, IL-6, IL-1β, TNF-α, and IFN-γ, is known to promote the expansion of immunosuppressive cells." (PMID 40822347, 2025). "In this study, we provide evidence that tumor-induced systemic inflammation activates NF-κB signaling in the hypothalamus, leading to upregulation of key pro-inflammatory genes (IL-1β, TNF-α and IL-6) within the CNS." (PMID 40993108, 2025). "Mechanistically, IL-1β has multifaceted pro-tumor effects: it upregulates other inflammatory mediators, enhances expression of adhesion molecules and matrix metalloproteinases, and promotes angiogenesis through induction of VEGF and other factors." (PMID 41007766, 2025). "IL-1β expression, induced by B cells, activates NF-κB signaling in tumor cells, upregulating proangiogenic genes such as VEGF, IL-8, and MMP2." (PMID 40868199, 2025). "The presentation of tumor-specific epitopes to DCs or macrophages triggers the release of inflammatory cytokines, such as IL-1β, IL-6, IL-12, and TNF-α, and the upregulation of CD80/86, which induces the formation of specific Th-1 cells and DC maturation." (PMID 41375025, 2025). "IL-1β stimulates tumor growth and metastasis by activating pathways that upregulate growth factors, such as TGF-β, prostaglandin (PGE)-2, and VEGF." (PMID 41179937, 2025). "In that study, the most abundant cytokine-receptor pair interaction between TAMs and tumor cells was predicted for IL1B and its decoy receptor IL1R2, suggesting inhibition of IL1B-mediated proinflammatory signaling by tumor cells." (PMID 40666494, 2025). "These IL-1β+ TAMs subsequently interact with IL-1β-reactive PC cells, thereby promoting tumor progression." (PMID 40948749, 2025). "Tumor-derived cues generally favor M2 polarization, resulting in the secretion of cytokines such as IL-4, IL-6, IL-1β, and TNFα." (PMID 40422235, 2025). "The downregulation of IL-1β and NF-κB inhibitor in MARCO deficiency further suggests the disruption of pro-inflammatory signaling pathways that typically sustain tumor-promoting chronic inflammation." (PMID 40695812, 2025).
tumor (continued). "By promoting the processing, maturation, and secretion of IL-1β and IL-18, it generates various biological effects, including drug resistance in tumor cells, by regulating the expression of inflammation-related genes." (PMID 40404908, 2025). "Cytokines including, IL-6, and IL-1β engage in positive feedback interactions with CCL2 in the TME—a phenomenon with important implications for tumor therapy." (PMID 41341593, 2025). "We also investigated the impact of targeting myeloid cell checkpoints together with T cell checkpoints on tumor growth by using anti-IL1B, anti-TREM2 or anti-IFITM, alone or in combination with anti-PD-1/CTLA4/LAG3." (PMID 40027748, 2025). "These cytokines represent complementary aspects of the tumor microenvironment: pro-inflammatory and tumor-promoting signaling (IL-6, IL-1β, TNF-α), anti-inflammatory modulation (IL-10), and Th17-driven immune activity (IL-17)." (PMID 41267807, 2025). "Pro-inflammatory cytokines, including IL-2, TNFα, IL-1β, and IL-6, contribute to shaping a tumor-promoting microenvironment by sustaining inflammation and facilitating cancer cell survival and dissemination." (PMID 41614846, 2025). "MSCs in the tumor microenvironment by pro-inflammatory cytokines IFN-γ, TNF-α, or IL-1β can be activated and secreted by macrophages and tumor cells." (PMID 39974358, 2025). "The activation of NF-κB is significantly increased in these cells, resulting in the secretion of cytokines such as IL6, TNFα, and IL1β, which subsequently promote cell proliferation and tumor viability." (PMID 40869207, 2025). "Preclinical studies have shown that interleukin (IL)-1β blockade can modulate the tumor microenvironment (TME) to activate antitumor immunity and, in combination with immune checkpoint inhibitors (ICIs), prevent cancer growth." (PMID 40116353, 2025). "IL-1β has been shown to promote macrophage polarization toward the pro-tumor M2 phenotype, while simultaneously inhibiting the anti-tumor activity of the M1 phenotype." (PMID 40109347, 2025). "By producing pro-inflammatory cytokines like TNF-α and IL-1β, neutrophils can enhance tumor cell proliferation and survival, thereby indirectly supporting tumor growth." (PMID 40486614, 2025). "ROS-mediated activation of NF-κB leads to the production of pro-inflammatory cytokines such as TNF, IL-1β, and IL-6, which further drive tumor-promoting inflammation." (PMID 41071399, 2025). "This tumor-driven IL-1β contributes to an inflammatory tumor microenvironment that fosters immunosuppression and supports tumor progression." (PMID 40558540, 2025). "First and foremost, the activation of GSDME significantly promotes the infiltration of immune cells into the tumor microenvironment through the release of inflammatory cytokines, such as IL-1β and IL-18." (PMID 40568597, 2025). "Recent studies have demonstrated that tumor-infiltrating monocytes differentiate into IL-1β-producing TAMs following exposure to prostaglandin E2 (PGE2) and TNF." (PMID 40948749, 2025). "IL-1, particularly IL-1β, plays a crucial role in initiating and maintaining inflammatory responses within the tumour microenvironment." (PMID 40234383, 2025). "In our direct co-cultures, we observed an early increase in IFN-γ secretion and enhanced tumor cell killing activity, followed by a decrease in IL-1β, IL-4 and IL-6 levels alongside an increase in soluble CXCL1." (PMID 40108668, 2025). "On the one hand, IL-1β administration induces rapid hypoglycaemia in mice, and injection of mice with IL-1β-secreting tumour cells decreases serum glucose levels by increasing glucose uptake by the peripheral tissues and decreasing hepatic gluconeogenesis." (PMID 39433211, 2025). "The coordinated action of TNF-α and IL-1β leads to a sustained CCL2 release from tumor and endothelial cells." (PMID 41341593, 2025).
tumor (continued). "Our data indicated that treatment with quadrigemine I significantly reduced the secretion of key pro-inflammatory cytokines, such as TNF-α, IL-6, and IL-1β, in various tissues, including serum, liver, spleen, and tumor tissues." (PMID 40429988, 2025). "Concurrently, tumor-derived IL-1β transforms resident fibroblasts into CAFs that subsequently secrete CXCL1, which stimulates the CXCR signaling cascade to potentiate metastatic dissemination." (PMID 41583435, 2025). "In preclinical studies, combining the IRAK4 inhibitor AS2444697 or IL-1β-neutralizing antibodies with gemcitabine significantly suppressed tumor growth and reduced fibrosis, highlighting the therapeutic potential of disrupting this signaling loop." (PMID 40948749, 2025). "Elevated expression of IL-1β can be observed in the immunological microenvironment of various solid tumors, primarily produced by immune cells, fibroblasts, and tumor cells." (PMID 40251177, 2025). "The IL-1β in the tumor microenvironment can induce the acetylation of histone H3, activating the expression of genes related to tumor progression." (PMID 40041484, 2025). "Recruited macrophages, in turn, activate IL-1β/IL-1R signaling in tumor cells, which further enhances LCN2 expression." (PMID 41436606, 2025). "The role of IL-1β in cancer is controversial, and its tumor promotion and tumor suppression aspects have been reported." (PMID 40244135, 2025). "This implies that IL-1β can modulate the immunosuppressive and pro-tumorigenic functions of TEVs, contributing to tumor progression and immune evasion." (PMID 40725070, 2025). "IL-1β is a key pro-inflammatory cytokine involved in inflammation, immune responses, and processes such as angiogenesis, fibrosis, and tumor progression." (PMID 40643749, 2025). "Clinically, elevated IL-1β expression in TNBC correlates with more advanced tumor stage, shorter recurrence-free survival, and reduced overall survival outcomes." (PMID 40868199, 2025). "In contrast, in the hypothalamus, the expressions of TNF-α, IL-6, IL-1β and NF-κB were elevated in the Tumor group of mice, which were all reversed by the treatment of PVSO group (p < 0.05)." (PMID 40993108, 2025). "Crosstalk between TAMs and tumor cells can further induce IL-1β (interleukin-1 beta)production, which relies on FAO to facilitate cancer cell migration." (PMID 41312365, 2025). "qPCR analysis of the dissociated tumour tissues showed that the delivery of Il‐12 minicircle‐loaded RBCEVs promoted the up‐regulation of pro‐inflammatory Ifng, Il‐1b and co‐stimulatory signal Cd86 in the tumours." (PMID 39193804, 2025). "IL-1β, IL-18, and TNF-α are known to be associated with tumour invasion, progression, and metastatic potential." (PMID 40430084, 2025). "On the other hand, loss of PRDX1 in macrophages restrains M2 polarization and enhances T‐cell‐mediated anti‐tumor immunity by promoting the secretion of inflammatory factors (IL‐1β and TNFα) via activation of JAK‐STAT1/NF‐κB signaling pathways." (PMID 41306557, 2025). "The NF-κB signaling pathway plays a key role in promoting pro-inflammatory cytokines, such as TNF-α, IL-1β, and IL-6, which are involved in tumor initiation and progression." (PMID 41154100, 2025). "Through a transglutaminase-2-dependent mechanism, IL-1β increases the aggressiveness of cancer cells in the tumor microenvironment by inducing the production of IL-6." (PMID 40699769, 2025). "In combination with a PAD4 inhibitor, short-term IL-1β inhibition led only to a statistically insignificant reduction in lung neutrophil recruitment, excluding neutrophils evoked by tumor cells." (PMID 41019086, 2025). "On day 23 after tumor implantation, we observed anti-IL-1β + anti-PD-1 had decreased tumor sizes compared to control." (PMID 39948655, 2025). "IL-1β is a key pro-inflammatory cytokine implicated in the progression of TNBC, primarily by enhancing angiogenesis and tumor invasiveness (see Section 3)." (PMID 40868199, 2025).
tumor (continued). "NF-κB-induced inflammatory cytokines, such as TNF-α, IL-1β, and IL-6, promote infiltration of tumor infiltrating macrophages (TAMs) and neutrophils into the tumor microenvironment, inhibiting cytotoxic T cell functions." (PMID 40169858, 2025). "Consistently, EZH2-high tumours in our cohort exhibit an IL-1β/RORC-dominated Th17 signature that likely fosters tumour progression." (PMID 41209556, 2025). "During inflammation, macrophages and tumor-associated cells secrete TNF-α and IL-1β, activating the NF-κB pathway and inducing COX-2 expression." (PMID 40978482, 2025). "Taken together, these findings highlight the importance of IL-1β produced by the immune cells in tumor progression, as further discussed in the following sections." (PMID 39858071, 2025). "Mechanistic studies revealed that Butein markedly downregulated the protein and mRNA expression of TWEAK, FN14, and TRAF1/2 in tumor tissue, and decreased serum levels of NF-κB-related inflammatory factors, including IL-1β, IL-6, IFN-γ, and TNF-α." (PMID 41458609, 2025). "When the semi-quantitative IRS values were compared between tumour tissues and the corresponding margins, TNF-α, IFN-γ, IL-12 and IL-2 showed relatively lower expression in tumours, whereas IL-1β and IL-6 were elevated in tumour tissue." (PMID 41465261, 2025). "We also analyzed the expression of M1 markers (IL‐1β, Nos2, TNFα) and M2 markers (Arg‐1, CD206, IL‐10) in tumor‐associated macrophages." (PMID 39791593, 2025). "For example, miR‐223 is a well‐documented miRNA that suppresses NLRP3 expression, thereby reducing the activation of the inflammasome and the consequent release of IL‐1β in tumor‐infiltrating macrophages and myeloid‐derived suppressor cells." (PMID 40671967, 2025). "These cells secrete cytokines and chemokines such as IL-1β, IL-6, and IL-8, which trigger inflammation and promote tumor growth." (PMID 41255580, 2025). "In head and neck cancer models, targeting SPP1+ macrophage derived cytokines, particularly TNF-α and IL-1β with the inhibitor significantly impaired tumor cell proliferation and migration in vitro and reduced tumor growth in vivo." (PMID 41425545, 2025). "AIM2 is essential for producing IL-1β and IL-18 that encourage the accumulation of Treg cells and tumor progression in vivo." (PMID 41291696, 2025). "This process leads to the release of interleukin-1β (IL-1β), which drives tumor progression and metastasis through paracrine signaling." (PMID 40755775, 2025). "In obesity-driven breast cancer, NLRC4 inflammasome activation in tumor-infiltrating macrophages enhances ANGPTL4 expression in mammary adipocytes via IL-1β, thereby driving tumor progression and angiogenesis." (PMID 40723247, 2025). "IL-1β enhances the presence of the granulocytic fraction (CD11b+Ly6G+Ly6Clow) in the initial tumor as well as the monocytic fraction (CD11b+Ly6ChighLy6G−) in metastatic tumors." (PMID 41291696, 2025). "Interleukin-1 beta (IL-1β) has been indicated to be capable of inducing the expression of numerous metastasis-related factors, thereby promoting tumor growth and metastasis." (PMID 40247422, 2025). "As a result, these TAK1 mutants defected TAK1's oncogenic functions to promote cancer cell proliferation, tumor growth in vivo, and elevate p65 downstream targeted genes such as TNFα, IL‐6 and IL‐1β.." (PMID 40999870, 2025). "Tumor-associated macrophages (TAMs), along with cytokines such as IL-1β, IL-6, and transforming growth factor-β (TGF-β), contribute to the establishment of a highly immunosuppressive and tumor-promoting niche." (PMID 40881678, 2025). "Solar UV–induced DNA damage robustly induces CD70 expression via E2F1, which in turn mediates keratinocyte and cSCC cell proliferation through MAPK and NF-κB signaling, driving the expression of inflammatory mediators and tumor-promoting factors such as IL1B." (PMID 41510255, 2025).
tumor (continued). "Elevated levels of IL-1β in the peripheral blood and tumor tissues have been linked to poorer survival rates in NSCLC, indicating the importance of further exploration into the prognostic implications of IL-1β." (PMID 40940992, 2025). "Lactate has also been shown to stimulate the release of interleukin (IL)-1β from TAMs in an inflammatory vesicle-dependent manner, with IL-1β further promoting TAM recruitment through the induction of C-C motif chemokine ligand 2 from tumor cells." (PMID 40165895, 2025). "The inflammatory factors produced during this process, such as IFN-β, TNF-α, IL-6, and IL-1β, play important roles in immune responses, collectively triggering systemic anti-tumor immunity and inhibiting tumor growth." (PMID 40756351, 2025). "EndMT is driven by factors such as TGF-β, IL-1β, and HIF-1α and is closely associated with tumor angiogenesis and stromal remodeling." (PMID 40244052, 2025). "Tumor-derived inflammatory cytokines, including IL-6, IL-1β, IL-8, GM-CSF, and VEGF, support the expansion, survival, and migration of MDSCs to the tumor site, establishing a chronic state of immune suppression." (PMID 40475782, 2025). "Activation of IL‐1β promotes lipid exchange between lung mesenchymal stromal cells, NK cells, and tumor cells, primarily through exosome‐like vesicles." (PMID 40959206, 2025). "Targeting key inflammatory mediators—such as the CCL2/CCR2 axis, CSF1R, or the IL-1β signaling pathway—has demonstrated promising anti-tumor effects in preclinical models." (PMID 40881678, 2025). "The bright red color indicates that the EAC group exhibited elevated levels of inflammatory markers (TNF, IL-1β, NF-κB), tumor markers (CA19, CA125, CA15), and oxidative stress indicators (MDA)." (PMID 41011277, 2025). "Concurrently, the IL-1β produced during this process stimulates tumor cells to secrete additional DAMPs, further amplifying inflammation." (PMID 40877572, 2025). "It was further identified that G-MDSCs targeted with an anti-IL-1β antibody provided survival benefits to female tumor-bearing mice, while M-MDSCs targeted with fludarabine extended survival in male tumor-bearing mice." (PMID 40244120, 2025). "Elevated expression of NLRP3 correlates with enhanced tumor growth, lymph node metastasis, and IL-1β expression; conversely, NLRP3 knockdown impairs proliferation, invasion, and metastatic capacity both in vitro and in vivo." (PMID 41560727, 2025). "In the present study, IL‐1β also exhibited a dose‐dependent increase, consistent with its established role in promoting tumor invasiveness and aggressive behavior through activation of signaling pathways." (PMID 40685820, 2025). "Proinflammatory cytokines, such as tumor necrosis factor-alpha (TNF-α), interleukin-1 beta (IL-1β), and interleukin-6 (IL-6), play a crucial role in shaping a proinflammatory tumor microenvironment." (PMID 40002704, 2025). "IL-1β promotes inflammation and facilitates tumor progression by promoting angiogenesis and attracting immunosuppressive cells." (PMID 41157253, 2025). "Tumor tissues can induce a systemic inflammatory response by secreting pro-inflammatory cytokines such as interleukin-6 (IL-6) and interleukin-1β (IL-1β), which stimulate bone marrow activity and lead to increased platelet production." (PMID 40837560, 2025). "In lung cancer, IR has been shown to promote tumor cell invasion and migration through the upregulation of IL-1β and its receptor, interleukin-1 receptor type I (IL-1RI) or II (IL-1RII)." (PMID 41211420, 2025). "And for cell culture cytokine measurements, found that the SAA signaling significantly influenced the releasing of many T cell maturation/polarization and anti-tumor immunity related cytokines including, IL-1β, IFN-γ, TNF-α, IL-6 etc.." (PMID 41488634, 2025).